ABCB4 (ATP binding cassette subfamily B member 4)
Diseases named in the same sentence as ABCB4 in open-access papers (continued):
Sharing a sentence is not in itself a finding about the gene and the disease.
cholestasis (continued). "Impaired ABCB4-mediated biliary phospholipid secretion was shown to be involved in itraconazole-induced cholestasis, where biliary PC levels were markedly reduced, while biliary bile salt levels remained unchanged." (PMID 36901890, 2023). "Administration of norUDCA, ASBT inhibitors, or a bile acid sequestrant have shown benefit in the Abcb4–/– mouse model of cholestasis and appear to involve overlapping and complementary therapeutic mechanisms of action." (PMID 36787187, 2023). "Here, we reviewed the leading molecular pathways between the DIC and ABCB1, ABCC2, ABCB11, and ABCB4 genes, the links with the other clinical forms of familial intrahepatic cholestasis, and, finally, the main cholestasis-inducing drugs." (PMID 36982896, 2023). "Homozygous mutations in ABCB4 and ABCB11 cause a spectrum of disease from mild cholestasis to severe progressive familial intrahepatic cholestasis (PFIC), PFIC3 and PFIC2 respectively." (PMID 37208429, 2023). "In the course of slowly progressing cholestasis, an increase in connective tissue remodeling was observed in the liver (black arrows, upper right) of untreated Abcb4-/- mice, and was most evident in the periportal fields (upper right)." (PMID 34954190, 2022). "Abcb4-/- mice represent a well-characterized model for sclerosing cholangitis beginning with persistent cholestasis that progresses to cirrhosis and liver failure before late childhood." (PMID 34954190, 2022). "Our aim is to investigate the effect of Abcb4 knockout-induced cholestasis on liver steatosis in HBs transgenic mice." (PMID 32612285, 2020). "Based on these findings, the present study was designed to investigate the effect of Abcb4 knockout-induced cholestasis on lipid metabolism in HBs transgenic mice." (PMID 32612285, 2020). "Absence of ABCB11 and ABCB4 proteins related to mutations in the ABCB11 and ABCB4 gene causes PFIC2 and 3 and leads to severe cholestatic liver disease in children that results in development of progressive cholestasis and liver cirrhosis." (PMID 31886153, 2019). "Correlation between GNMT and miR-873-5p in human cholestasis and cirrhosis together with miR-873-5p inhibition in vivo in different mouse models of liver cholestasis and fibrosis [bile duct ligation and Mdr2 (Abcb4)-/- mouse] were then assessed." (PMID 30237481, 2018). "It is well known that both Fxr and Abcb4 genes ablation in mice leads to liver damage, fibrosis, cholestasis and spontaneous HCC induced by high level of hydrophobic cytotoxic BAs." (PMID 30464200, 2018). "Important genes known to play a role in cholestasis such as ABCB4 (MDR3), ABCB11 (BSEP) and NR0B2 (SHP) were downregulated in human PCLS exposed to bile acids and cholestatic drugs." (PMID 27344345, 2017). "This is supported by pre-existing data on the role of ABCB4 in cholestasis and by the correlation of cholestasis with fetal arrhythmia and adult AF/AFL." (PMID 25888430, 2015). "MDR3 encoded by the ABCB4 gene, moves the phosphatidylcholine chemical, a substance found in eggs, soybeans, mustard, sunflower and other foods on the inner to the outside leaflet of lipid bilayer which results in various types of cholestasis." (PMID 40125297, 2025). "Recent literature report that cholestasis may also be related to mutations in genes encoding bile acid metabolic transporters such as ABCB11, ABCB4, ABCCC2, ATP 8B1, TJP2, which result in the abnormal function of bile salt export pump in hepatocytes." (PMID 38191339, 2024). "This implied that cholestasis was aggravated as a result of cholecystectomy in Abcb4-/- mice, which was confirmed by a significant increase in total bile acid content in the liver of cholecystectomized vs. sham-operated Abcb4-/- mice." (PMID 36923239, 2023). "Inhibition of ABCB4 by drugs may lead to cholestasis and drug-induced liver injury (DILI), although compared with other drug transporters, there are only a few identified substrates and inhibitors of ABCB4." (PMID 36901890, 2023).
cholestasis (continued). "Although the loss of viral genomes could be a problem for most inherited cholestasis, ABCB4 deficiency, which causes PFIC3, has certain advantages over other PFIC types for liver gene therapy." (PMID 35740260, 2022). "We hypothesized that the pharmacologic antagonization of CB1 receptor improves cholestasis in Abcb4-/- mice." (PMID 34954190, 2022). "On the other hand, a Th1-shift improved cholestasis in Abcb4−/− mice." (PMID 32846954, 2020). "Thereby, immunohistochemical assessment of ABCB11 and ABCB4 may be useful to determine the degree of cholestasis as well as the disease progression in PSC patients." (PMID 31886153, 2019). "In this study, we show that liver fibrosis progression is associated with the repression of GNMT, which is targeted by miR-873-5p in two preclinical models of liver fibrosis and cholestasis: the bile duct ligation (BDL) and the Mdr2 (Abcb4)-deficient mice (Mdr2-/-), respectively." (PMID 30237481, 2018). "The extent of liver damage, cholestasis, and fibrosis was enhanced in Abcb4−/−/HBsAg+/− mice." (PMID 28881751, 2017). "Interestingly, ABCB4-/- knock-out mice had low secretion of PC into the bile, leading to cholestasis and liver fibrosis." (PMID 25888430, 2015). "In addition, some missense mutations in less conserved regions of the ABCB11 and ABCB4 genes promote the development of more moderate variants of cholestasis such as BRIC2, ICP, cholesterol cholelithiasis, drug-induced cholestasis, adult biliary cirrhosis, transient neonatal cholestasis, and others." (PMID 35740260, 2022). "However, as illustrated by other studies, GGT levels alone may not reliably differentiate between cholestasis linked to ABCB4 and ABCB11 variants, since some ABCB4 variants may not show elevated GGT levels." (PMID 41436587, 2025). "In contrast, total liver bile acid levels were significantly increased by Abcb4 deletion in both wild-type and CYPDKO mice, suggesting that liver cholestasis occurred due to Abcb4 deletion." (PMID 39111549, 2024). "Similarly, studies with multidrug resistance gene 2 (Mdr2 or Abcb4)-deficient mice, another mouse model of genetically induced cholestatic liver disease, have shown that the absence of a gut microbiota worsens cholestasis and liver phenotype and leads to increased lethality." (PMID 37384590, 2023). "The enhanced number of infiltrated CD45+ leukocytes in Abcb4-/- mice was abolished by rimonabant, which indicates an anti-inflammatory effect of pharmacologic CB1 antagonization during cholestasis." (PMID 34954190, 2022). "Fourteen patients presented with chronic or recurrent high GGT level cholestasis and one PV or LPV in ABCB4." (PMID 35626323, 2022). "In our model, the impact of ER-stress on hepatocyte damage during cholestasis is shown by the phosphorylation of ER-stress-dependent PERK and eIF2α in Abcb4−/− mice, which was reduced by the IL-13−/−-knockout." (PMID 32846954, 2020). "Serum parameters for liver damage and cholestasis (ALT, AST, AP) were significantly elevated in Abcb4−/− compared to corresponding wild-type mice in all diet groups." (PMID 25191532, 2014). "Among the 15 pediatric patients, 11 with biallelic ABCB4 mutation were diagnosed with PFIC3; four patients with non-biallelic mutations were diagnosed as DILI, cirrhosis cholestasis, cirrhosis, and mild liver fibrosis respectively." (PMID 38610052, 2024). "Similar results were also found on Abcb4−/−- and DDC-induced cholestasis models." (PMID 38539789, 2024). "For this purpose, a non-obstructive model of cholestasis, the Abcb4-/- model resembling sclerosing cholangitis, was utilized." (PMID 37307826, 2024). "Furthermore, in MDR2(Abcb4)-null mice, and control mice fed with a 3,5-diethoxycarbonyl-1,4-dihydrocollidine (DDC)-supplemented diet that leads to cholestasis, platelets activate HSCs through PDGF-β secretion and promote fibrosis." (PMID 38138981, 2023).
cholestasis (continued). "In cholestasis, UDCA may contribute to therapeutic effects by inducing alternative excretory routes for bile acids and other cholephiles through activating ABCB4." (PMID 35924060, 2022). "Lack of IL-13 protected Abcb4−/− mice transiently from cholestasis." (PMID 32846954, 2020).
liver fibrosis (61 papers, 2010 to 2026). "Variants in the ABCB4 gene are associated with various cholestatic phenotypes, some of which progress to liver fibrosis and cirrhosis." (PMID 36397154, 2022). "To investigate the potential anti-fibrogenic effects of CM414, we used a clinically relevant animal model of chronic portal inflammation and bile duct proliferation with progression to liver fibrosis and cancer (Mdr2/Abcb4-deficient mice (Mdr2-KO))." (PMID 33322158, 2020). "In the Abcb4 knockout mice, cholecystectomy caused an increase in hepatic bile acid content and in circulating secondary bile acids, and an aggravation in cholangitis, inflammation and liver fibrosis." (PMID 36923239, 2023). "In addition to the lack of phospholipids in bile, all these abnormalities can cause liver fibrosis and cirrhosis in ABCB4 KO mice, with its liver pathology being similar to that of PFIC3 patients." (PMID 35741809, 2022). "Here, using BA related Abcb4−/− and Fxr−/− mouse models of spontaneous hepatic fibrosis and HCC, we explored the role of a novel engineered variant of FGF19 protein, called FGF19-M52, which fully retains BA regulatory activity but is devoid of the pro-tumoral activity." (PMID 30464200, 2018). "Next, liver fibrosis caused by collagen fiber deposition was analyzed because the expression of liver fibrosis marker genes was upregulated by Abcb4-deletion in CYPDKO mice." (PMID 39111549, 2024). "In this context, its employment resulted in an amelioration of liver fibrosis in the cholestatic Abcb4-/- model." (PMID 37307826, 2024). "In the Abcb4 knockout mouse model of PSC, cholecystectomy causes an aggravation of cholangitis and liver fibrosis." (PMID 36923239, 2023). "Five repeat ABCB4 mRNA-LNP injections were able to restore ABCB4 expression and biliary PC levels (~42% of wild-type levels), as well as improve serum biomarker levels, liver fibrosis, and hepatomegaly." (PMID 35740260, 2022). "ABCB4 deficiency induces chronic liver inflammation and progressive hepatic fibrosis in Abcb4−/− mice." (PMID 34360670, 2021). "Using a nutritional model of NASH (atherogenic diet including cholesterol and cholic acid) and a genetic model of liver fibrosis (Mdr2-/- mice, ABCB4 KO mice), we showed that the hepatic cholesterol level regulates the disease phenotype." (PMID 32566088, 2020). "Abcb4−/− mice lack the hepatocanalicular phosphatidylcholine floppase ABCB4 and develop sclerosing cholangitis and liver fibrosis." (PMID 25191532, 2014). "However, plasma transaminases elevations, liver fibrosis, and ductular reactions were markedly aggravated by Abcb4-KD in the context of a human-like BA composition." (PMID 41962761, 2026). "•Cholecystectomy aggravates cholangitis and liver fibrosis in Abcb4 knockout mice." (PMID 36923239, 2023). "However, the protective effect of rimonabant in Abcb4-/- mice is congruent with other models of chronic liver damage such as CCl4-induced, thioacetamide-induced, and bile duct ligation–induced liver fibrosis." (PMID 34954190, 2022). "Hepatic fibrosis was clearly reduced in 52-week-old Abcb4−/−/IL-13−/− mice (p = 0.002)." (PMID 32846954, 2020). "The aim of our study was to compare by parametric magnetic resonance imaging the standard model of liver fibrosis based on CCl4 intoxication and the ATP-binding cassette transporter B4 knockout (Abcb4 −/−) mouse model of PSC and to relate results to the severity of liver fibrosis." (PMID 28194423, 2017). "Mice lacking the hepatocanalicular phosphatidylcholine transporter ABCB4 develop liver fibrosis spontaneously, resemble patients with sclerosing cholangitis due to mutations of the orthologous human gene, and represent a valid model to study tumour formation in pre-injured cholestatic liver." (PMID 27391331, 2016). "In addition, 52-week-old Abcb4−/−IL-13−/− mice showed significantly reduced hepatic fibrosis." (PMID 32846954, 2020).
liver fibrosis (continued). "Data obtained in Abcb4/Mdr2−/− (canalicular phospholipid export pump/multidrug resistance protein 2) mice, representing a well characterized model system for sclerosing cholangitis and biliary type of liver fibrosis, suggest potential direct anti-inflammatory and anti-fibrotic effects of norUDCA." (PMID 25463533, 2015). "Among ABC transporters, ATP-binding cassette subfamily B member 4 (ABCB4) is involved in the efflux of bile salts in gut bacteria and also influences the intestinal absorption of vitamin D, thereby preventing liver fibrosis." (PMID 41395487, 2025). "Moreover, polymorphisms such as rs2109505 (c.711A>T, p.I237=) in ABCB4 and rs2287622 (c.1331T>C, p.V444A) in ABCB11 are more prevalent in adult patients with idiopathic cholestasis than in healthy controls representing risk factors for the development of liver fibrosis." (PMID 35884482, 2022). "In this sense, an AAV8 vector expressing ACE2 was able to reduce liver fibrosis in early- and late-stage FVB Abcb4-/- mice." (PMID 35740260, 2022). "Hence, we hypothesized that vitamin D supplementation ameliorates liver fibrosis in vivo by phenotyping Abcb4 (ATP-binding cassette transporter, subfamily B, member 4) knockout (Abcb4−/−, also known as Mdr2−/−) mice, an established and highly reproducible model of sclerosing cholangitis." (PMID 25191532, 2014). "Four children and five adults with non-biallelic ABCB4 mutations were phenotypically diverse, ranging from DILI, ICP, and LPAC, to liver transplantation due to severe liver fibrosis (one child)." (PMID 38610052, 2024). "In a second study, performed by our group, we evaluated PFIC3 AAV-based gene therapy in FVB Abcb4-/- mice, which have a clinically relevant phenotype characterized by high serum levels of bile salts and transaminases, hepatosplenomegaly, and liver fibrosis." (PMID 35740260, 2022). "An AAV8 vector was used to deliver ATP binding cassette subfamily B member 4 (ABCB4) in a murine model of progressive familial intrahepatic cholestasis 3, leading to stable ABCB4 expression and the amelioration of the progression of liver fibrosis." (PMID 32785089, 2020). "Lack of the Abcb4 gene elicits a plethora of detrimental cell responses, including hepatic fibrosis, thus laying the foundation to hepatocarcinogenesis." (PMID 30464200, 2018). "Taken together, these findings suggest that low vitamin D levels aggravate liver fibrosis, but supranormal vitamin D levels have no additive antiinflammatory or -fibrotic effects in Abcb4−/− mice." (PMID 25191532, 2014). "Based on previously observed substantial anti-fibrotic effects of 24-nor-ursodeoxycholic acid (norUDCA) in Abcb4/Mdr2−/− mice with cholestatic liver injury and biliary fibrosis, we hypothesized that norUDCA improves inflammation-driven liver fibrosis in S. mansoni infection." (PMID 25463533, 2015).
liver disease (47 papers, 2007 to 2026). "Reduced biliary PC and increased concentrations of lysophosphatidylcholine, sphingomyelin, and ceramide were associated with the severity of liver disease only in Cyp2c70-KO/Abcb4-KD mice." (PMID 41962761, 2026). "Out of the 9 cases, 4/9 (44.4%) had a known diagnosis of metabolic dysfunction associated steatotic liver disease (MASLD) of whom 3/4 (75%) had an ABCB4 LoF and 1/4 (25%) had an ABCB11 LoF variant." (PMID 41436587, 2025). "Mutations on the ABCB4 gene have been associated with several liver diseases (LPAC, ICP, DIC, transient neonatal cholestasis) and only anecdotally with episodic FIC in later age." (PMID 39984942, 2025). "Variants of the ABCB4 gene, encoding for MDR3, are related to a broad spectrum of liver diseases, but also to mental impairment, growth retardation and reduced bone density, and, notably, to an increased probability of developing CCA." (PMID 39984942, 2025). "A possible explanation is that multiple factors, including hormones, the environment, and other genetic factors, contribute to the occurrence of ABCB4 deficiency-related liver diseases." (PMID 38610052, 2024). "In a large Icelandic population study, ABCB4 polymorphisms were not only associated with rare monogenic liver diseases but also with chronic liver diseases." (PMID 37511794, 2023). "Gene variations of ABCB4 cause different types of liver diseases, including progressive familial intrahepatic cholestasis type 3 (PFIC3)." (PMID 35203270, 2022). "Another example is ABCB4, a hepatic phospholipid transporter, whose loss in human patients results in bile canaliculi damage and severe liver disease." (PMID 33575564, 2020). "Together with the genetic evidence, patient histories, and animal studies, these data at the protein level provide a compelling argument that the ABCB4 genotype can underlie development of inflammatory liver diseases that extends to cancer." (PMID 28220208, 2017). "Here, we report the first characterisation at the protein level of six ABCB4 variants (D243A, K435T, G535D, I490T, R545C, and S978P) previously found in patients with inflammatory liver diseases or liver cancer." (PMID 28220208, 2017). "Non-synonymous SNPs in ABCB4 have now been described in patients with liver cancer or with inflammatory liver diseases that are known to predispose to cancer, but data showing that the SNPs are sufficiently deleterious to be an etiological factor are lacking." (PMID 28220208, 2017). "Combining what is already known about the role of ABCB4 in bile formation and flow, with the animal data and human genetic data, it seems plausible that ABCB4 SNPs underlie the inflammatory liver disease in these patients." (PMID 28220208, 2017). "ABCB4 harbors numerous missense mutations which probably reflect the spectrum of liver disease depending on ABCB4 background." (PMID 28881751, 2017). "The severity of the liver disease in ABCB4 deficiency ranges from biochemical abnormalities with annoying symptoms to life-threatening disease with the potential for progression to death due to hepatic failure." (PMID 26900700, 2016). "Multidrug resistance protein 3 (MDR3, ABCB4) deficiency is among those liver disorders associated with impairment of the canalicular transport of bile constituents." (PMID 26900700, 2016). "A retrospective study shows that, in 233 patients with juvenile lithiasis, those who have mutated ABCB4 have a greater number of abnormalities in magnetic resonance (MR), have more frequent calculosis, and greater susceptibility to advanced liver disease, CCA and secondary sclerosing cholangitis." (PMID 39984942, 2025). "These protective mechanisms are known to be critical for the health of the biliary tree, because pedigree analysis shows definitively that mutations in ATP8B1 and ABCB4 cause two forms of fatal liver disease: Progressive Familial Intrahepatic Cholestasis (PFIC) types 1 and 3, respectively." (PMID 28220208, 2017).